IL15 (interleukin 15)
Diseases named in the same sentence as IL15 in open-access papers (continued):
Sharing a sentence is not in itself a finding about the gene and the disease.
tumor (continued). "Interleukin-15 (IL-15) has been used to prime the tumor microenvironment (TME) to boost the efficiency of immunotherapy." (PMID 40532661, 2025). "Our study focuses on the effects of intraperitoneal administration of an anti-PD-1 mAb in combination with intratumorally delivered IL-15 complexes in luminal B tumor-bearing mice." (PMID 41373645, 2025). "Combining IL-15 with radiotherapy in mice has been found to activate and recruit dendritic cells (DCs) into the tumor, promoting NK and CD8+ T cell expansion through IL-15 trans-presentation by DCs." (PMID 40532661, 2025). "In this study, we evaluated the combination of CD25-targeted NIR-PIT and intratumoral IL-15 administration with anti-PD-1 mAb in treating syngeneic murine tumor models." (PMID 41410776, 2025). "This enhances NK cell proliferation further while augmenting the antitumor effects of CAR-NK cells in tumor microenvironment (TME) with limited levels of specific cytokines (such as IL-15)." (PMID 40705122, 2025). "DIG was detected on tumor cell surfaces, indicating that intratumorally injected IL15-DIG bound to the cell surface in the tumor." (PMID 40886193, 2025). "IL-15 shows potential in PC treatment by promoting the generation, proliferation, and activity of anti-tumor NK cells and CD8+T cells, thereby enhancing the immune response against tumors." (PMID 39958351, 2025). "The anti-tumor activity of t-haNK PD-L1 cells was evaluated in combination with anti-PD-1 and an IL-15 superagonist (N-803)." (PMID 40299429, 2025). "Conversely, IL-15, which is currently under investigation in clinical trials, stimulates anti-tumor immunity directly by promoting the proliferation and activation of CD8+ T cells and by activating NK/NKT cells." (PMID 40386779, 2025). "This antigen-dependent expression system led to selective IL-15 expression following tumor recognition and improved tumor control in a xenograft mouse model of gastric cancer." (PMID 41019052, 2025). "Although this study did not include histological vascular assessments, the VEGF stabilization aligns with previous reports in murine models where IL-15 administration led to reduced tumor vascularization." (PMID 40552079, 2025). "Taken together, all these data reinforce the fact that Sell(hi) neutrophils enhanced p‐Stat5+CD8+Tpex‐mediated tumor cell killing through IL15‐stat5a axis." (PMID 40936164, 2025). "A clinical trial demonstrated that IL-15 administration significantly improved the survival of infused γδT cells in patients with cancer and boosted their anti-tumor activity." (PMID 40226616, 2025). "Tumor-localized IL-15 delivery minimized systemic toxicity—a critical advancement given the dose-limiting hepatotoxicity of conventional IL-15 therapies." (PMID 40873574, 2025). "We observed significant up-regulation of IL-15 signaling genes in tumor-infiltrating NK clusters, including IL15, IL2RB, IL2RG, STAT5B, and JAK1." (PMID 40315330, 2025). "IL15 is involved in immune cell infiltration to tumour sites, and CEBP stimulates Inflammatory marker IL6." (PMID 40434957, 2025). "B7-H6M4LC21 exhibited enhanced tumor-killing efficacy (IC50: 5 ng/mL) compared to B7H6M4-OKT3(IC50: 1 ng/mL) when combined with an IL-15/IL-15Ra sushi fusion protein, which augmented NK cell proliferation and cytotoxicity." (PMID 40873574, 2025). "To further understand the potential interactions between immune cells, we also performed an analysis of cytokine expression genes in tumours; the most expressed cytokines were TGFβ, IL-18, IL-15, and TNFα." (PMID 41301032, 2025). "IL-2, in cooperation with cytokines such as IL-15, plays a pivotal role in enhancing the anti-tumor functions of natural killer (NK) cells." (PMID 40869161, 2025). "Previous studies on multiple IL-15-based CAR-T therapies targeting GPC-3 or CLDN18.2 have primarily focused on directly attacking tumor cells." (PMID 41455698, 2025).
tumor (continued). "This design mitigates IL15 toxicity by confining drug release specifically to the local tumor site where TCR activation occurs." (PMID 40612864, 2025). "Preclinical models have further shown that IL-15 can break immune tolerance and stimulate effective anti-tumor mechanisms." (PMID 41196843, 2025). "In anti-GBM therapy, CAR-TTS−2021 cells can use the IL15 synthesized and released by OAd-infected tumor cells to maintain their functional activity." (PMID 40474210, 2025). "Solutions for CAR NK therapy includes engineering NK cells for better survival, using cytokines like IL-15, combining them with immune checkpoint inhibitors, and improving tumor infiltration through tumor-homing receptors or nanoparticles." (PMID 39859231, 2025). "The rILR-Fc/PhA/rIL-15 NPs enhanced the tumor accumulation of PhA and IL-15 through FcRn-mediated endocytosis and micropinocytosis." (PMID 40430906, 2025). "For instance, dual-antigen–sensing CAR platforms can trigger IL-15 or IL-21 secretion only in tumor-restricted contexts, offering an added safety layer." (PMID 41584600, 2025). "All treatment interventions increased CD8+ T cell density in the tumor area, with only the Combination + anti-PD-1 group showing a significant increase compared to the Control, IL-15, and NIR-PIT groups (b left)." (PMID 41410776, 2025). "Contrarily, human γδ thymocytes inherently lean toward differentiating into γδ T cells upon stimulation with IL-2 or IL-15, and are consequently more inclined to exhibit anti-tumor effects within the TME." (PMID 40148988, 2025). "Other types of CAR-T cells, such as 4/15NKG2D-CAR and IL-4/IL-21 ICR, also show anti-tumor activity; the former converts IL-4 inhibitory signals downstream into IL-15 activation signals, while the latter activates the STAT3 pathway." (PMID 39958351, 2025). "Serial sections from OCT blocks were obtained from EO771 tumor-bearing mice 48 h after the second treatment with either the IL-15 complex and anti- or control IgG antibody and stained for CD8, CD45, and PanCK to identify CD8+ TILs and tumor cells." (PMID 41373645, 2025). "At the same time, IL-15/IL-15Rα complex-secreting NKG2D-CAR T also showed superior anti-tumor activity and survival in vivo." (PMID 40625735, 2025). "We used RNA from whole-tumor lysates isolated from tumor-bearing (EO771) mice that had received IL-15 complexes and anti-PD-1 mAb or an IgG isotype control antibody for these experiments." (PMID 41373645, 2025). "When primed by inflammatory cytokines (IFN-γ, TNF-α, IL-1β), MSCs secrete IL-15, IL-12, and type I interferons, which are critical for maintaining NK cell cytotoxicity and survival in hostile tumor settings." (PMID 40643499, 2025). "These engineered CAR-T cells demonstrate increased tumor infiltration rates compared to control-activated T cells or IL-15-overexpressing NKG2D CAR-T cells." (PMID 40612946, 2025). "In summary, our results indicate that syngeneic IL-15/IL-12-conditioned NK cell therapy promotes tumor-specific T cell responses, at least in part, through activation of cDC1s and cDC2s in metastatic lung." (PMID 39835538, 2025). "CAR-NK cells engineered to express IL-15 have demonstrated increased persistence and improved anti-tumor responses in vivo." (PMID 41425568, 2025). "Our previous study has shown that the downstream signaling pathway of IL-15 can enhance the anti-tumor activity of NKG2D-CAR T cells and promote the generation of memory T cells." (PMID 40625735, 2025). "Oncolytic vaccinia viruses express IL-2, IL-10, IL-12, IL-15, IL-21, IL-23, IL-24, and IL-36γ remodel the tumor microenvironment,enhance immune cell infiltration, suppress immunosuppressive elements and promot systemic antitumor immunity." (PMID 40469178, 2025). "The subsequent generation of primary CAR-NK cells directed against CD44v6, incorporating an IL-15 superagonist and checkpoint inhibitor molecules, exhibited effective anti-tumour activity against 3D spheroid models and resistance to the TME." (PMID 40650066, 2025).
tumor (continued). "designed PSCA CAR_s15 NK cells, which enhance IL-15 activation of NK cells, improving tumor cell killing efficiency and showing significant inhibitory effects on PSCA-positive PC cells." (PMID 39958351, 2025). "Next-generation approaches integrate safety modules: (i) CRISPR-mediated CD70 knockout to prevent fratricide, (ii) cytokine-secreting armored CARs (e.g., IL-15) to counter immunosuppression, and (iii) logic-gated systems to reduce off-tumor toxicity." (PMID 40896423, 2025). "Recent research highlights the role of STAT5-related cytokines (IL-2 and IL-15) in tumor immunotherapy efficacy, with IL-15 cytokines inhibiting tumor growth and preventing metastasis, making them promising cancer treatment strategies." (PMID 39996811, 2025). "Among them, preconditioning NK cells with interleukin-2 (IL-2) and interleukin-15 (IL-15) has shown promise in enhancing both their expansion and cytolytic performance against tumor cells." (PMID 41567203, 2025). "The 4αβ chimeric cytokine receptor is a synthetic receptor that mimics IL-2/IL-15 signaling, enabling enhanced T-cell proliferation and persistence in the hostile tumor microenvironment." (PMID 40312353, 2025). "The results demonstrated a significant enhancement in the anti-tumor efficacy of CAR-T cells armed with IL-15 and CCL19, characterized by more robust and rapid tumor control." (PMID 40177238, 2025). "IL-15 activates critical immune cells, including natural killer (NK) cells and cytotoxic T cells, thereby enhancing tumor cell lysis and supporting the long-term survival of memory T cells." (PMID 40520425, 2025). "More advanced fourth-generation CARs, known as T cell Redirected for Universal Cytokine Killing, are engineered to secrete immunostimulatory cytokines like IL-12, IL-15, or IL-18, thereby enhancing anti-tumor efficacy and modulating the tumor microenvironment." (PMID 40677703, 2025). "Our findings provide robust preclinical evidence supporting the targeted elimination of both CAFs and tumor cells positive for FAP by FAP/IL-15 CAR-T cells, underscoring their potential utility as adoptive cellular immunotherapies." (PMID 41455698, 2025). "Collectively, these findings demonstrate that IL-15 co-expression induces a mixed program of effector differentiation and increased proliferative capacity that correlates with improved anti-tumor activity." (PMID 41154636, 2025). "Administering IL-15 fused with IL-15Rα (IL-15/IL-15Rα) directly into tumors boosts tumor cell destruction and expands NK and CD8+ T cells." (PMID 40636453, 2025). "This suggests that IL-15 secretion by FAP/IL-15 CAR-T cells is efficient, stable, and capable of overcoming uneven drug distribution caused by the tumor-stromal barrier." (PMID 41455698, 2025). "While IL-15 and tetrac show great potential, their therapeutic use remains underexplored, especially in complex tumor environments." (PMID 39811313, 2025). "This approach results in the creation of a biohybrid bacterial system designed to selectively deliver IL-15 to the tumor site, promoting localized immunomodulation." (PMID 40532661, 2025). "In pre-cancerous mammary lesions, IL-15 secreted by tumor cells was shown to induce GzmB production in CD103+ cytotoxic ILC1s, contributing to early tumor surveillance." (PMID 40963622, 2025). "Mechanistically, this involves the release of cytokines such as IL-15, which supports T cell mobilization and tumor infiltration, strengthening anti-tumor immunity." (PMID 40519261, 2025). "Mice treated with C‐P plus anti‐IL15 or anti‐Ly6G antibody had less inhibition of tumor growth than those treated with C‐P alone." (PMID 40936164, 2025). "In preclinical tumor models, this approach has demonstrated strong antitumor effects, outperforming both single agent IL-15 superagonist and single agent anti-PD1 therapy, as well as their combination in melanoma models (AACR poster 2023)." (PMID 40410571, 2025).
tumor (continued). "Multiple IL‐15 agonists, such as RLI, ILR, NIZ985, and pro‐IL‐15, have already been utilized in the treatment of different tumor models." (PMID 40799128, 2025). "Here, we investigated the molecular design of tumor-directed trifunctional antibody-cytokine fusion proteins for a combinatorial approach of IL-15 with either IL-7 or IL-21." (PMID 40370435, 2025). "IL-15 stimulates activation, proliferation cytotoxic activity of NK cells, but its clinical use is prevented by short half-life, poor accumulation in the tumor, and toxicity due to systemic off-target immune activation." (PMID 40213559, 2025). "In this study, we reported that engineering CAR-NK cells to express IL-21 resulted in enhanced anti-tumor activity compared to CAR-NK cells expressing IL-15." (PMID 40176196, 2025). "We next investigated the expression of integrins, ligands, and receptors that were differentially expressed on the tumor 48 h after the second treatment with either PBS/IgG isotype or IL-15 complexes, or after anti-PD-1 therapy." (PMID 41373645, 2025). "These properties make IL-15 an ideal candidate for combination therapies designed to overcome tumor immune evasion and improve therapeutic outcomes." (PMID 40520425, 2025). "To generate NK cells with anti-tumor activity ex vivo, we cultured murine bone marrow (BM) cells with IL-15 and IL-12, since IL-15 is an NK cell growth and survival factor and both cytokines enhance IFN-γ production and the cytotoxicity of NK cells." (PMID 39835538, 2025). "At low dose of 3 mg kg-1, four out of six mice treated with Pembrolizumab-IL-15Rα-IL-15 were free of tumor development, while tumor sizes of the other two mice were much smaller than that of control." (PMID 39808627, 2025). "NK cells also contribute to this network by supporting CD8+ T cell–mediated tumor clearance through IL-15–mediated cross-talk and complementary cytotoxic mechanisms." (PMID 40971094, 2025). "Using a hydrogel for the local sustained release of IL-15/IL-15Rα supercomplex or IL-12 can directly increase the cytotoxic function of NK cells against residual tumor cells." (PMID 41149727, 2025). "This therapy utilizes cord blood-derived NK cells transduced with a CAR targeting TROP2 and an IL-15 support gene, designed for IP delivery, to enhance tumor targeting in the peritoneal cavity." (PMID 40643516, 2025). "Specifically, IL-15 has been shown to promote memory-like characteristics in γδ T cells, while IL-21 enhances their cytotoxic capabilities against tumor cells." (PMID 40227601, 2025). "Unlike systemic IL-15 therapies (e.g., ALT-803) that promote Treg expansion and hepatotoxicity, our design confines IL-15 activity to B7-H6+ tumors, analogous to PD-L1-targeted IL-12 strategies that improve tumor-specific immunity." (PMID 40873574, 2025). "In CRC models, combining IL-15-expressing oncolytic adenoviruses with cytotoxic T lymphocytes (CTLs) has demonstrated superior tumor suppression, reinforcing the potential of virotherapy in immuno-oncology." (PMID 40507337, 2025). "Mice treated with the combination of anti-PD-1mAb (i.p.), and two doses of IL-15 complexes (i.t.)showed reduced tumor growth compared to tumors of mice in both single modality treatments and the control (PBS/IgG isotype) group." (PMID 41373645, 2025). "MSC-derived IL-15 plays a central role in sustaining NK cell survival and proliferation, particularly in nutrient-deprived or immunosuppressive tumor environments." (PMID 40643499, 2025). "These biomarker changes align with the known effects of IL-15 on enhancing tumor suppression through both immune activation and metabolic pathways, potentially improving treatment outcomes." (PMID 40520425, 2025). "Armoring CAR-NK cells with IL-15 in their construct enhances their in vivo persistence and improves their metabolic fitness, leading to enhanced anti-tumor activity." (PMID 41511303, 2025).
tumor (continued). "Transgenic expression of IL-15 in CAR T cells targeting GD2 significantly enhanced tumor control in an orthotopic glioblastoma model." (PMID 40895575, 2025). "Upon intravenous (IV) dosing to tumor-bearing mice, ACTM-838 distributed and enriched in the TME, exhibited specific uptake in tumor-resident phagocytic cells and led to expression of human IL-15/IL15Rα and murine IFNα in the tumor." (PMID 41048107, 2025). "Mice were taken down 12 days after the initial inoculation of EO771 tumors or 2 days after the second IL-15 complex and anti-PD-1 treatment, and the tumor and tumor-draining lymph node were removed and placed in OCT blocks." (PMID 41373645, 2025). "Neospora caninum, a potential anticancer agent able to reactivate the immune response within the tumor microenvironment (TME), has recently shown enhanced immunomodulatory properties in different tumor models when armed with the cytokine, Il-15." (PMID 40236994, 2025). "Engineered in CAR constructs, IL-15 has been proven to be effective in supporting and enhancing the anti-tumor cell function both in solid and blood cancers." (PMID 41465318, 2025). "IL-15 has been shown to promote the survival and proliferation of these effector cells, enhancing their cytotoxic activity against tumor cells." (PMID 40552079, 2025). "At the time of tumor gene analysis, the average tumor sizes of mice treated with control, anti-PD-1 mAb alone, IL-15 complexes alone, or a combination of anti-PD-1 mAb and IL-15 complexes are shown." (PMID 41373645, 2025). "By engineering LiPSC-GR1.1 with a mesothelin (MSLN)–targeting CAR and interleukin-15 (IL-15), we achieved robust differentiation of iPSCs into mature activated iNK cells with enhanced tumor killing efficacy, superior tumor homing, and vigorous proliferation." (PMID 40315330, 2025). "A more direct approach involves newer generations of CAR T cells designed to release cytokines such as IL-15 or IL-18, which can repolarize myeloid cells at the tumor site, enhancing the anti-tumor efficacy of CAR T cells." (PMID 40050933, 2025). "We previously reported that intratumoral IL-15 administration in combination with tumor-targeted NIR-PIT enhances anti-tumor immunity while avoiding the side effects of systemic IL-15 administration." (PMID 41410776, 2025). "Combination therapy with B7-H6M4-LC21 (10 mg/kg) and B7-H6M18/IL-15/IL-15Ra sushi (0.03 mg/kg) achieved synergistic tumor inhibition (p<0.05), surpassing the efficacy of T cell-based combinations." (PMID 40873574, 2025). "EcN/IL-15 + L combined with anti-PD-1 antibodies significantly suppressed tumor growth, achieving complete tumor rejection in 43% of mice (3/7), versus 14% (1/7) with EcN/IL-15 + L alone." (PMID 40532661, 2025). "To determine if EO771 tumor-bearing mice treated with IL-15 complexes and/or anti-PD-1 therapy effectively cleared tumors and were protected from further tumor regrowth, we rechallenged these animals." (PMID 41373645, 2025). "Cytokine transfection is a technique that utilizes gene editing to introduce or amplify specific cytokines, such as IL-15 and IL-2, to enhance NK cell survival, proliferation, and function, thereby augmenting their anti-tumor effects." (PMID 40391220, 2025). "Upon reaching the tumor, the liposome cleaved and release IL-15 and IDO1 inhibitor while draining into LNs in a size-dependent manner." (PMID 40159756, 2025). "A prerequisite for successful IL15‐based treatments is the adequate infiltration of effector cells into the tumor." (PMID 39625860, 2025). "Unrestricted IL-15 delivery risks off-target Treg activation, underscoring the necessity for tumor-localized cytokine delivery systems." (PMID 40873574, 2025). "Recently, a next-generation immunocytokine, LH05—a tumor-conditional anti-PD-L1/IL-15 prodrug—has been developed to minimize systemic toxicity by masking IL-15 until it is enzymatically activated within the TME." (PMID 40281554, 2025).